VDR (vitamin D receptor)
Diseases named in the same sentence as VDR in open-access papers (continued):
Sharing a sentence is not in itself a finding about the gene and the disease.
Hypocalcemia (continued). "Thus, developmental dysregulation and hypocalcaemia in VDR‐KO models preclude the identification of a post‐natal role of the VDR in skeletal muscle." (PMID 33258480, 2021). "Further, 1,25(OH)2D3 regulates calcium and phosphorus homeostasis in mineral-regulating organs, such as the intestine, bone, kidney, and parathyroid glands by binding to vitamin D receptor (VDR), and has been widely used to treat hypocalcemia, metabolic bone diseases, hypoparathyroidism, and cancer." (PMID 33238436, 2020). "Therefore, it is not possible to dissect the effects that direct loss of vitamin D signalling has from those of elevated PTH and hypocalcaemia on cardiac function in global VDR knockout mice kept on a normal diet." (PMID 30273386, 2018). "Interestingly, our data suggested that the decrease in PTG CaSR expression, which is important in the development of SHPT, was caused by the early decrease in PTG Gcm2 expression, followed by the effect of 1,25(OH)2D reduction, PTG VDR reduction, hypocalcemia and hyperphosphatemia." (PMID 32517664, 2020). "The vitamin D receptor (VDR) knockout (KO) mouse is a common model to unravel novel metabolic functions of vitamin D. It is recommended to feed these mice a high calcium (2%), high phosphorus (1.25%) diet, termed rescue diet (RD) to prevent hypocalcaemia and secondary hyperparathyroidism." (PMID 28443031, 2017). "Subsequently, low calcitriol levels and hypocalcemia induced by increasing FGF23 levels indirectly stimulate PTH synthesis and release in the parathyroid via VDR and CaSR, overriding the inhibitory action of FGF23." (PMID 35269640, 2022). "As a result, low calcitriol levels and hypocalcemia promote PTH synthesis and release via VDR and CaSR in parathyroid, overriding the inhibitory effect of FGF23." (PMID 35269640, 2022). "Animal studies have shown that VDR(−/−)/RXRG(−/−) mice exhibit features typical of vitamin D-dependent rickets type II, including growth retardation, impaired bone formation, hypocalcemia, and alopecia." (PMID 24641809, 2014). "Neither the absence of vitamin D or the vitamin D receptor nor hypocalcemia affected the ability of mice to mount an antibody response to an antigen challenge." (PMID 36341456, 2022). "The authors aimed to address this by feeding a calcium- and phosphorus-enriched rescue diet, and by examining mice at 20 days of age with the rationale that hypocalcemia in VDR knockout mice is not yet developed at this early stage." (PMID 36501215, 2022). "To assess the isolated effects of lacking vitamin D signalling in the absence of hypocalcemia on survival and heart function after MI, we analysed sham and MI, WT and VDR mutants on rescue diet at 2 and 8 weeks post-surgery." (PMID 30273386, 2018). "In our experimental setting, moderate hypocalcaemia (Σ2.1 mmol/L total calcium) in VDR mutant mice on normal diet did not have major detrimental effects on heart function after MI relative to normocalcaemic VDR mutant mice on rescue diet." (PMID 30273386, 2018). "Five patients who showed hypocalcemia (<8.0 mg/dl at 1 week), without clinical symptom, recovered soon after increased doses of vitamin D receptor activators and/or calcium-based phosphate binder." (PMID 28912972, 2017). "Serum calcium was comparable at 2, 8, 12, 14, and 16 months of age in VDR WT and KO mice, suggesting that the high calcium rescue diet is sufficient to prevent hypocalcemia in VDR KO mice regardless of age." (PMID 21298063, 2011). "Finally, experiments from my lab showed that the VDR knockout mouse phenotype (e.g., hypocalcemia, elevated serum PTH, low bone mineral density) can be completely prevented by intestine epithelial cell-specific, transgenic expression of VDR that normalizes intestinal Ca absorption." (PMID 36014856, 2022).
Hypocalcemia (continued). "However, because of the ubiquitous expression of the VDR and the perturbation of mineral metabolism in these mice, it is difficult to distinguish if these effects are due to severe hypocalcemia or if they are indeed due to lack of the VDR in the parathyroid." (PMID 36501215, 2022). "In addition, we found an interaction between genotype and MI for the left ventricular relaxation time constant, i.e., the normal diet and subsequent hypocalcaemia aggravated diastolic dysfunction only in VDR mutant but not in WT mice." (PMID 30273386, 2018). "In any case, our findings suggest that sHPT and hypocalcaemia, rather than the absence of cardiac VDR, may be primarily involved in the decline of cardiac function post-MI in global VDR deficient mice on a normal diet reported earlier." (PMID 30273386, 2018). "Importantly, the altered mammary gland development observed in both young and aged VDR KO mice occurred in the absence of hypocalcemia, indicating that these effects of VDR ablation are not secondary to the role of VDR in maintenance of extracellular calcium homeostasis." (PMID 21298063, 2011). "It has been demonstrated that mice lacking the vitamin D receptor (VDR) gene display retarded growth, severe bone impairment, immune abnormalities, and premature death at only 15 weeks of age due to hypocalcemia." (PMID 24782782, 2014).
liver fibrosis (54 papers, 2013 to 2025). "Genetic VDR deletion in mice exacerbated liver fibrosis progression, which was associated with elevated TGF-β1 levels and increased Smad3 phosphorylation." (PMID 40514735, 2025). "In this study, we demonstrated that VDR deficiency exacerbates hepatic fibrosis by triggering metabolic reprogramming in HSCs." (PMID 40514735, 2025). "It has recently been suggested that vitamin D receptor (VDR) polymorphism is associated with liver fibrosis chronicity." (PMID 39654627, 2024). "Polymorphisms in the VDR gene were also associated with the severity of liver fibrosis in patients with biopsy-proven NAFLD and with liver enzyme activity in NAFLD patients treated with calcitriol." (PMID 37175993, 2023). "To note, VDR polymorphisms have been associated with the severity of liver fibrosis in patients with biopsy-proven NAFLD, supporting the notion that VDR affects insulin-sensitive tissues and organs such as adipose tissue and the liver." (PMID 35955597, 2022). "In parallel, the progression of liver fibrosis was associated with the presence of VDR polymorphisms in PBC, HCV, liver cirrhosis, and NAFLD." (PMID 35955597, 2022). "VDR FokI rs2228570 TT/TC genotypes were also suggested as risk factors for advanced liver fibrosis in HCV patients." (PMID 32235600, 2020). "The current study showed that the VDR FokI rs2228570 TT/TC genotypes and age ≥55 years were independent risk factors for advanced liver fibrosis in Thai patients with chronic HCV infection." (PMID 31565578, 2019). "This study aimed to investigate the associations of VDR polymorphisms with advanced liver fibrosis and response to pegylated interferon (PEG-IFN)-based therapy in patients with chronic HCV infection." (PMID 31565578, 2019). "In a cohort of G1CHC patients, lower hepatic VDR expression of VDR protein has been found to be associated with the severity of both liver fibrosis and inflammation." (PMID 29449867, 2018). "It was clearly demonstrated that enhanced progression of liver fibrosis is significantly and independently associated with both genetic VDR variants and low 25-OH vitamin D plasma levels." (PMID 26504859, 2015). "In this study, we hypothesized that the differential expression of VDR is implicated in the progression of liver fibrosis by regulating the activation of HSCs." (PMID 35043727, 2022). "However, the interpretation of the role of TaqI and BsmI variants in the development of liver fibrosis is hindered because only limited information is available on the functional changes induced by these variants of the VDR gene." (PMID 32727130, 2020). "The present study demonstrates an association between the VDR bAt (CCA) haplotype and poor response to PEG-IFN plus ribavirin therapy and associations between the VDR FokI rs2228570 TT/TC genotypes and advanced liver fibrosis in Thai patients with chronic HCV infection." (PMID 31565578, 2019). "Moreover, in a cohort of G1CHC patients, the hepatic expression of VDR protein is associated with severity of both liver fibrosis and inflammation." (PMID 26273302, 2015). "Given the established role of the VDR in fatty acid metabolism regulation, we investigated the involvement of the VDR in the SI-mediated attenuation of hepatic fibrosis." (PMID 40514735, 2025). "Collectively, these data position VDR as a central regulator of lipid metabolism disorders that drive liver fibrosis progression." (PMID 40514735, 2025). "As infection progresses, the expression level of miR-351 increases, and the inhibitory effect of vitamin D receptor (VDR) on the Smad signalling pathway is released via targeting of VDR, promoting the development of liver fibrosis." (PMID 40462224, 2025). "This research not only reveals a previously unrecognized metabolic regulatory mechanism of VDR in liver fibrosis but also offers novel therapeutic avenues for combating hepatic fibrosis through metabolic reprogramming strategies." (PMID 40514735, 2025).
liver fibrosis (continued). "Ligand-activated VDR has been shown to effectively suppress HSCs activation and attenuate extracellular matrix deposition in hepatic fibrosis." (PMID 40514735, 2025). "This study elucidates the critical role of VDR in hepatic fibrogenesis, particularly its novel mechanism of attenuating liver fibrosis through modulation of fatty acid metabolism in HSCs." (PMID 40514735, 2025). "HSC activation drives liver fibrosis via fatty acid metabolic reprogramming, with VDR identified as a key transcriptional regulator." (PMID 40514735, 2025). "OPN-neutralizing antibody induced trNKT cells VDR up expressions, and it is crucial for their modulation of liver fibrosis." (PMID 39654627, 2024). "We have previously demonstrated vitamin D’s impact on alleviating liver fibrosis via improving NK cell cytotoxicity and upregulating VDR on NK cells." (PMID 39654627, 2024). "Calcipotriol, a novel VDR agonist, was shown to reduce liver fibrosis in vivo by inhibiting the activation of HSCs and the deposition of ECM." (PMID 37175993, 2023). "Some of these studies also suggested that VDR activation helps in the prevention of hepatic fibrosis in chronic liver injury." (PMID 37153919, 2023). "Considering these aspects, it is worth investigating that VDR, which is the receptor of VitD3, is related to liver fibrosis and presents its clinical application potential." (PMID 35043727, 2022). "Previous study showed that VDR/Smad co‐occupied the regulatory region of Col1α1 and VDR showed stronger combinatory activity, thus inhibiting transcription of Col1α1 to inhibit liver fibrosis." (PMID 35906886, 2022). "Together, we firmly believe that the VDR-mediated calcipotriol treatment exerted an anti-liver fibrosis effect by regulating fibrosis-related factors in vivo." (PMID 35043727, 2022). "Based on the liver tissue pathological specimens of patients with liver fibrosis, we detected the correlation between the expression of VDR, α-SMA, as well as Col-1 and the degree of liver fibrosis." (PMID 35043727, 2022). "In this approach, calcipotriol, a VDR agonist, was employed to effectively reduce liver fibrosis in rat and cell models of liver fibrosis." (PMID 35043727, 2022). "Calcipotriol, a selective VDR agonist, offers a specific anti-hepatic fibrosis effect in animal models with liver cirrhosis." (PMID 35043727, 2022). "The binding of vitamin D to VDR results in the decreased proliferation of HSCs and contributes to the alleviation of liver fibrosis." (PMID 35955597, 2022). "As a receptor for active vitamin D, the expression of VDR in liver tissue and its relationship with liver fibrosis are worthy of our further study." (PMID 35043727, 2022). "Based on the CCl4-induced rat model of liver fibrosis and TNF-α stimulated cell model of HSCs, we demonstrated that VDR regulated progression of liver fibrosis and cell function of HSCs with the participation of NF-κB signaling pathway." (PMID 35043727, 2022). "The expression of VDR in liver tissues of patients with liver fibrosis is negatively correlated with α-smooth muscle actin (α-SMA), Col-1, and liver fibrosis stages." (PMID 35043727, 2022). "Further, a rat model with carbon tetrachloride (CCl4)-induced liver fibrosis is employed to verify the effect and mechanism of VDR on the process of liver fibrosis in vivo." (PMID 35043727, 2022). "Accordingly, we aimed to systematically study the effect of VDR on liver fibrosis and the possible mechanisms for regulating liver fibrosis and provide a potential target for the treatment of liver fibrosis." (PMID 35043727, 2022). "Vitamin D receptor (VDR) signaling promotes the dissociation of the Smad proteome from DNA to inhibit liver fibrosis." (PMID 36389166, 2022). "To further verify the effect of VDR on liver fibrosis in vivo, we constructed an SD rat liver fibrosis model through CCl4 treatment." (PMID 35043727, 2022).
liver fibrosis (continued). "At the same time, activation of vitamin D receptor signaling pathway can inhibit the proliferation of hepatic stellate cells and improve liver fibrosis in NAFLD patients." (PMID 34006273, 2021). "Other studies have suggested the role of VDR, VDBP gene polymorphisms in the progression of liver diseases such as inflammation and liver fibrosis." (PMID 34836382, 2021). "Another study that determined SNPs of the VDR gene in NAFLD-proven subjects with liver biopsy has shown VDR rs1544410 genotype CC to be independently correlated with advanced liver fibrosis." (PMID 34836382, 2021). "Put together, these data suggest that VDR activation by calcipotriol alleviates liver fibrosis and injury in cholestasis through inhibition of NLRP3 signal, and calcipotriol inhibits HSC activation by inhibiting NLRP3 pathway both directly and indirectly." (PMID 32296329, 2020). "In our chronic fibrotic model, serum vitamin D levels was unchanged as compared to WT mice and progressions of liver fibrosis were due to inhibitions of VDR in HSCs." (PMID 32276660, 2020). "One of the mechanisms for VD-dependent alleviation of hepatic fibrosis was via the VDR-dependent downregulation of the transforming growth factor (TGF) β-1/small mothers against decapentaplegic (SMAD) 3 pathway." (PMID 32235600, 2020). "VDR knockout mice develop spontaneous liver fibrosis, demonstrating that the VD/VDR signaling pathway regulates hepatic fibrogenesis." (PMID 31781188, 2019). "Recently, Wahsh and colleagues, using a TAA animal model of fibrosis, found that the VDR agonist, calcipotriol, modulates fibrogenic pathways and mitigates liver fibrosis in-vivo when injected via the intraperitoneal route at a dose of 80 ug/kg." (PMID 29659559, 2018). "It is reported that administration of VDR agonist reduced collagen deposition and fibrotic gene expression in mouse models with hepatic injury, while VDR knockout mice developed liver fibrosis spontaneously." (PMID 28878195, 2017). "Thus far, at the clinical level, the concept that low VD may influence and be related to the severity of liver fibrosis is supported by clinical observations based on histological evidence, liver stiffness measurements and the association with VD/VDR metabolic pathway polymorphisms." (PMID 28827788, 2017). "Liver fibrosis in the VDR KO was previously reported and here using Masson's Trichrome staining, we confirmed the issue." (PMID 27895587, 2016). "Vitamin D is involved in inhibition of inflammation and abrogation of liver fibrosis, substantiated by the observation that vitamin D receptor knockout mice spontaneously develop hepatic fibrosis." (PMID 27659316, 2016). "Vitamin D receptor (VDR) ligands can decrease liver fibrosis by redirecting VDR to SMAD3 sites on the DNA, thereby reducing SMAD3 occupancy." (PMID 28933415, 2016). "VDR has been demonstrated to behave as an antagonist to Smad3 and prevent liver fibrosis in stellate cells." (PMID 27456065, 2016). "The anti-fibrotic potential of VDR stimulation was confirmed by reduced fibrosis in a rat model of liver fibrosis." (PMID 23540496, 2013). "The VDR is another dimerization partner of RXR involved in liver fibrosis." (PMID 39478961, 2024). "Animal studies have found that VDR-knockout mice develop liver fibrosis." (PMID 38413933, 2024). "The VDR agonist calcifertriol reduces liver fibrosis in a mouse model of liver injury." (PMID 39144288, 2024). "Moreover, VDR activity has been reported to inhibit liver fibrosis by suppressing the expression of pro-fibrotic genes mediated by TGF-β1/SMAD signaling." (PMID 37511164, 2023). "Consistently, VDR agonists protected against CCL4-induced liver fibrosis." (PMID 36899928, 2023). "The elevated plasma VDR levels may indicate increased VDR activity, which has been reported to inhibit liver fibrosis by suppressing the TGF-β1/SMAD signaling-mediated expression of pro-fibrotic genes." (PMID 37511164, 2023).